PIWIL2 (piwi like RNA-mediated gene silencing 2)
Diseases named in the same sentence as PIWIL2 in open-access papers (continued):
Sharing a sentence is not in itself a finding about the gene and the disease.
cancer (continued). "Consistently with these data, our results demonstrated that Piwil2 overexpression or induction by E6 and E7 significantly increased the level of H3K9ac and reduced H3K9me3, which led to the upregulation of the cancer stem-like cell gene-sets." (PMID 27602489, 2016). "Knockdown of Piwil2 by shRNA led to a marked reduction in proliferation and colony formation, in vivo tumorigenicity, chemo-resistance, and the proportion of cancer stem-like cells." (PMID 27602489, 2016). "PIWIL2 was increased both at the RNA and protein level in malignant cancer tissues compared with adjacent normal tissue." (PMID 26373553, 2015). "In recent years, many research groups have managed to demonstrate overexpression of PIWIL2 in various human cancers." (PMID 25384072, 2014). "Expression of PIWIL1 and PIWIL2 has been found in a wide range of human cancers such as stomach, breast, gastrointestinal tract and endometrium and recently also in ovarian carcinoma." (PMID 24932571, 2014). "The human PIWI subfamily of Argonaute proteins comprise 4 members, PIWIL1/HIWI, PIWIL2/HILI, PIWIL3 and PIWIL4/HIWI2, all found in testis, although recently a number of reports have identified elevated expression of HIWI and HILI in a variety of human cancers." (PMID 25313140, 2014). "The volume of data on expression profiles of PIWIL2 in different cancers suggests its implication in carcinogenesis and has prompted many research groups to propose it as an oncological marker." (PMID 25384072, 2014). "Our moleculardata were consistent with Piwil2 reprogrammingrole in the emergence or prevalence of cancer stemcell population (paper in press)." (PMID 24027667, 2013). "To investigate the signaling pathway through which Piwil2 suppresses the apoptosis of cancer cells, we studied the relationship between Piwil2 and its potential target genes." (PMID 22303479, 2012). "It has been reported that Piwil2 transcripts were widely detected in various tumors or cancer cell lines, and played important roles in tumorigenesis and apoptosis inhibition." (PMID 22303479, 2012). "Recently, expression of PIWIL2 has been widely detected in a variety of tumor cell lines as well as in various stages of primary cancers." (PMID 22110608, 2011). "We and others have reported that Piwil2 proteins or Piwil2 transcripts were detected in various types of cancers or cancer cell lines." (PMID 20975993, 2010). "PIWIL2 dysregulation has been shown to influence several fundamental cellular processes, including proliferation, cell cycle progression, and the DNA damage response, across multiple cancer types." (PMID 39849644, 2025). "Moreover, the overexpression of PIWIL2 in some cancers leads to cellular cisplatin resistance, possibly because increased chromatin condensation affects normal DNA repair." (PMID 39849644, 2025). "Notably, PIWIL2 has been proposed as a promising target in different types of cancer because of its capacity to promote cell proliferation and inhibit apoptosis." (PMID 39849644, 2025). "Thus, it has been shown that Piwil2-induced cancer stem cells (Piwil2-iCSCs) increase the expressions of MMP2 and MMP9, which are responsible for enhanced invasiveness and migration through exosomes." (PMID 38667297, 2024). "An increasing number of studies have reported aberrant expression of PIWIL2 in cancer." (PMID 38303021, 2024). "PIWIL-2 is essential for the proliferation and escape from apoptosis of a variety of cancer cells." (PMID 32166374, 2020). "In addition, induction of PIWIL2 was also reported to endow cancer stem cell-like properties to human fibroblasts with ectopic expression of these stemness markers." (PMID 33374923, 2020). "Additionally, cancer specific mutations have been revealed including a PIWIL1 mutant (P1∆17) which lacks an exon 17 and a PIWIL2 mutant (PL2L60) with a truncated PAZ domain." (PMID 33374923, 2020). "Only two carcinomas showed a slight upregulation of PIWIL-2." (PMID 32166374, 2020).
cancer (continued). "Similarly, piR-932 and PIWIL2, which constitutes a bridge between cancer stem cells (CSCs) and proliferation and anti-apoptosis, form a complex to promote latexin promoter CpG island methylation in BC stem cells." (PMID 31399034, 2019). "This activation is dependent on cellular milieu rather than the integrity of host gene PIWIL2, highlighting a novel, important mechanism for a cancer-causing gene to be activated during tumorigenesis." (PMID 28545024, 2017). "Here we present that PIWIL2 represses circadian rhythms both in the testis and cancer cells." (PMID 28903391, 2017). "This demonstrates that PIWIL2 expression promotes genetic instability that is reminiscent of the abnormal chromosomal segregation and aneuploidy that is characteristic of many types of cancer." (PMID 28103575, 2017). "This hypothesis is supported by the fact that knockdown of PIWIL2 can recover the disrupted circadian system in HeLa cancer cells to a certain extent." (PMID 28903391, 2017). "The potential importance of PIWIL2 in the development of cancer stem cells has recently been demonstrated by the production of cancer stem cell like cell lines in vitro by transfection of mouse embryonic fibroblasts with a full length cDNA copy of the mouse PIWIL2 gene." (PMID 28103575, 2017). "Also, our further study on HeLa cancer cells showed consistent results that PIWIL2 suppresses the interaction between GSK3β and BMAL1, leading to the failure of ubiquitination and degradation of the latter protein." (PMID 28903391, 2017). "It has been reported that the expression of Piwil2 and Piwil4 in malignant tumors may be related to the occurrence, development, and prognosis of tumors." (PMID 27894076, 2017). "This study indicates that the PIWIL2 gene could play a key role in cancer induction and maintenance." (PMID 28103575, 2017). "Overall, our findings indicate that Piwil2 may act as a key initial factor in the formation of cancer stem-like cells, which suggests that the cancer stem-like cell signature is reactivated to some extent during the course of tumor progression." (PMID 27602489, 2016). "In particular, Piwil2 is predominantly expressed in cancer stem cells (CSCs) and in precancerous stem cells (pCSCs), indicating that it might play an important role in tumor initiation." (PMID 27602489, 2016). "Studies have recently demonstrated that PIWIL2 is expressed in precancerous and cancer stem cells." (PMID 26496203, 2015). "PIWIL2, which is one of the genes upregulated (4.8-fold) in mTeSR1 compared to MEF-CM hESC cultures, is associated with suppression of apoptosis in cancer stem cells and may underpin the reduced apoptosis seen in mTeSR1-grown cultures." (PMID 25639500, 2015). "In particular, PIWIL2 has been probed as a potential neoplasia biomarker in many cancers in humans." (PMID 25384072, 2014). "PIWIL2 was demonstrated to impact the development of precancerous stem cells into cancers." (PMID 25384072, 2014). "For example, the majority of traditional anti-cancer drugs are genotoxic, and the resulted DNA-damage may activate PIWIL2 gene to promote DNA repair in the targeted tumor cells." (PMID 22110608, 2011). "As a consequence, the Piwil2-mediated DNA repair may spare the tumor cells from the anti-cancer drug-induced apoptosis." (PMID 22110608, 2011). "Elucidation of the role of Piwil2 in signaling cell transformation and tumorigenesis will provide new insights into the biological functions of PIWIL2 and potential therapeutic targets in cancer treatment." (PMID 22110608, 2011). "To determine whether PL2L60 was also predominantly expressed in native cancers in addition to tumor cell lines, we attempted to generate murine monoclonal antibody (mAb) to Piwil2 and PL2L60 or other PL2L proteins." (PMID 20975993, 2010). "However, PIWIL2 function in cancer initiation and development is rather controversial, and remains unclear." (PMID 31443431, 2019).
cancer (continued). "Thus, in cancers, the overexpression of PIWIL2 is key evidence in the malignant and pernicious." (PMID 26373553, 2015). "Thus, Piwil2 expression induced by the chemotherapeutic agents such as cisplatin might contribute to drug resistance of tumor cells such as cancer stem cells." (PMID 22110608, 2011). "This may also explain why little Piwil2 was detected in primary cancers." (PMID 22110608, 2011). "Therefore, we propose that a cancer can develop from a lengthy process of benign proliferation → precancer → cancer, which is mediated by TISCs, pCSCs and CSCs, respectively; and the process might be controlled and/or modulated by Piwil2 and PL2L proteins." (PMID 20975993, 2010). "In addition to Piwil2 and PL2L proteins, other GSC and embryonic stem cell genes might be the potential candidates of cancer-causing genes." (PMID 20975993, 2010). "There are four known human PIWI homologs: PIWIL1 (HIWI), PIWIL2 (HILI), PIWIL4 (HIWI2), and PIWIL3 (HIWI3), all of which have been shown to be expressed in a number of different cancer tissues." (PMID 39596284, 2024). "In previous studies, PIWIL1, PIWIL2, and PIWIL4 have been reported to function in cancer cell proliferation, metastasis, and invasion." (PMID 38033031, 2023). "In addition, research indicated that PIWIL1 and PIWIL2 expression were significantly increased in invasive ductal carcinomas (IDCs), inducing a stem-like state of cancer cells through abnormal DNA methylation, generating genomic silencing and ultimately promoting cancer development." (PMID 35637965, 2022). "This family contains four subtypes which any of them has a different role in cancer cells (PIWIL1 or HIWI, PIWIL2, PIWIL3, and PIWIL4)." (PMID 34193172, 2021). "Our comprehensive analysis revealed a more differentiated pattern where PIWIL1, MAEL and HENMT1 had increased expression, while PIWIL2, PIWIL4 and TDRD1 had decreased expression when comparing benign and malignant tumor samples." (PMID 33374923, 2020). "The four human PIWI proteins PIWIL1, PIWIL2, PIWIL3 and PIWIL4 can be included in the cancer/testis antigens (CTAs) class and their deregulation is involved in cancer cell proliferation, apoptosis and stemness, genomic integrity, invasion and metastasis." (PMID 33008024, 2020). "Some of these pathway genes (PIWIL1, PIWIL2, TDRD1 and MAEL) are categorized as cancer/testis genes due to their restricted expression in testis but in recent years, have been observed to be aberrantly expressed in multiple cancers." (PMID 33374923, 2020). "On the other hand, PIWIL2 and PIWIL4 show low expression in many normal tissues and are upregulated in several cancer types, while PIWIL3 is almost undetectable in all tissues considered, except germline." (PMID 31694219, 2019). "Knockdown of HDAC3 reduced the effect of PIWIL2 on cancer cell proliferation or apoptosis, indicating that HDAC3 was involved in the role of PIWIL2 on cancer proliferation and apoptosis." (PMID 29555935, 2018). "Most importantly, the forced expression of Piwil2 led to a clear upregulation of ALDH, MSCA-1, and ABCG2, three common markers of cancer stem-like cells, as detected by FACS, and a significant LD50 increase of cisplatin, as determined by a CCK8 assay." (PMID 27602489, 2016). "In this study, we used two novel candidate stem cell markers, PIWIL2 and TPGB/5T4, to detect putative CSCs in cancer patients." (PMID 26496203, 2015). "Among them, PIWIL2 (MILI in mice, HILI in humans) has been repeatedly proposed as a potential marker for cancers of various origin." (PMID 25384072, 2014).
cancer (continued). "However, it is notclear whether Piwil2 has a role(s) in developmentof CSC populations or it is consequence of cancer.Thus, in the present study, the MEF-Piwil2 cellline was established, while the effect of Piwil2 expression on its molecular and functional behaviorwas investigated." (PMID 24027667, 2013). "Notably, PIWIL2, a member of the PIWI protein subfamily, is widely expressed in tumors and leads to cancer progression 41-44." (PMID 38993562, 2024). "Moreover, a study about PIWIL2 demonstrated that PIWIL2, as well as PIWIL1, can be a biomarker for CRC because of its higher expression in this kind of cancer." (PMID 34193172, 2021). "In the paratumor tissues, PIWIL2 expression can not be observed at protein level; while all carcinoma tissues showed notable expression of PIWIL2 mRNA and protein." (PMID 33469229, 2021). "Based on a meta-analysis of TCGA and GTEx data, we found that PIWIL1 presents unique features among PIWILs, as PIWIL2 and PIWIL4 are frequently deregulated in cancers but are also expressed in several normal tissues, while PIWIL1 is almost absent in non-transformed tissues." (PMID 31694219, 2019). "PIWIL2 promoted cancer cell proliferation via increasing c-Myc expression by facilitating NME2 binding to the G4-motif, facilitated cancer cell migration via TBCB and resisted Fas-induced cancer cell apoptosis by inhibiting keratin 8 degradation." (PMID 29555935, 2018). "Previous researches including ours indicated that PIWIL2 belongs to the category of cancer/testis antigens (CTA) that expressed in human tumors but not in normal adult tissues except for testis." (PMID 28903391, 2017). "The results reveal that PL2L60 rather than Piwil2 are constitutively and widely expressed in various types of cancers without the restriction of tissue origin." (PMID 20975993, 2010). "Based on the information, we generated novel polyclonal and then monoclonal antibodies to a peptide shared by Piwil2 and PL2L proteins of humans and mice and identified four PL2L proteins, including PL2L80, PL2L60, PL2L50, and PL2L40, in the testis and cancer cell lines of humans and mice." (PMID 20975993, 2010). "The LIN28/let‐7 axis has been reported to facilitate aerobic glycolysis to promote cancer progression.[14b] In this study, PIWIL2 overexpression in HaCaT cells induced LIN28 upregulation, particularly that of LIN28A, and PDK1, which also were observed in HCBC stably transfected with PIWIL2 or E6." (PMID 39499767, 2024). "Moreover, also HIWI or PIWIL1, PIWIL2, and PIWIL4 (members of PIWI subfamily) have been proven to play important roles in cell proliferation and apoptosis in several types of cancers." (PMID 34193172, 2021). "However, the difference in expression level for PIWIL1 versus PIWIL2 and PIWIL4 contributing to better patient outcome was expected given the difference we observed when comparing their expression in benign and malignant tumors as well as low grade OC versus high grade OC." (PMID 33374923, 2020). "In contrast, no upregulation of PIWIL-2 in carcinomas was found." (PMID 32166374, 2020). "Furthermore, PIWIL1 and PIWIL2 are significantly elevated in invasive ductal carcinoma (IDC), which promotes cancer development by aberrant DNA methylation resulting in genomic silencing and inducing a stem-like state of cancer cells." (PMID 31399034, 2019). "Piwil2, a member of Ago/Piwi gene family containing Piwi and PAZ domains, hasbeen shown to be ectopically expressed in different cancer cells, especially its remarkable expression in cancer stem cells (CSCs), and is also known to be essential for germ line stem cellself-renewal in various organisms." (PMID 24027667, 2013). "The functions of Piwil2 and PL2L proteins might override those of cancer-contributing genes." (PMID 20975993, 2010).
cancer (continued). "Thus, IBCs with PIWIL2–PIWIL4 downregulation could benefit from immunotherapy by using checkpoints inhibitors because of an important cytotoxic immune reaction and reexpression of many neoantigens and TEs by cancer cells." (PMID 33008024, 2020). "They found that while genes like PIWIL1, PIWIL2, PLD6 (Zucchini), and DDX4 (VASA) were expressed in some cancer cell lines, their expression alone was not enough to form functional piRNA-PIWI silencing complexes (piRISCs)." (PMID 39717847, 2024). "We could detect no expression of paralogues in H460, with A2780 expressing PIWIL2 and relatively low levels of PIWIL4; however, the levels of neither were significantly altered by TEX19 depletion, suggesting that TEX19 regulation of PIWI gene expression may not be universal in all cancer cell types." (PMID 28446200, 2017).